CCL2 (C-C motif chemokine ligand 2)
Diseases named in the same sentence as CCL2 in open-access papers (continued):
Sharing a sentence is not in itself a finding about the gene and the disease.
breast cancer (continued). "Reference 53 to “Kitamura, T.; Qian, B.Z.; Soong, D.; Cassetta, L.; Noy, R.; Sugano, G.; Kato, Y.; Li, J.; Pollard, J.W. CCL2-induced chemokine cascade promotes breast cancer metastasis by enhancing retention of metastasis-associated macrophages." (PMID 31146450, 2019). "In summary, these data indicate that increased CCL2/CCR2 signaling in SUM225 breast cancer cells promotes cell proliferation, and invasion associated with increased TWIST1 and decreased E-cadherin." (PMID 31208996, 2019). "CCL2/CCR2-mediated breast cancer progression was associated with increased growth, invasion and decreased tumor cell apoptosis." (PMID 31208996, 2019). "Previous researches have assessed the association between CCL2-2518A/G (rs1024611) polymorphism and cancer risk, including breast cancer, lung cancer, gastric cancer, bladder cancer, ovarian cancer, and others." (PMID 29458367, 2018). "Use of CCL2 versus CCR2 knockout mice further revealed that deficiency in CCL2 resulted in delayed outgrowth of mammary carcinoma, while deficiency in CCR2 enhanced tumor outgrowth." (PMID 30233579, 2018). "The increase in stroma, collagen and mammary cancer risk in Mmtv-Ccl2 mice resembled key clinical and histological features of HMD in women." (PMID 28077158, 2017). "We propose that CCL2-driven inflammation contributes to the increased risk of breast cancer observed in women with HMD." (PMID 28077158, 2017). "CCL2 expression in breast carcinomas is highly associated with macrophage infiltration, and its expression is correlated with poor prognosis in breast cancer patients." (PMID 28077158, 2017). "CCL2 is both positively and negatively associated with the growth of several tumor types, including breast cancer." (PMID 28143493, 2017). "We propose that CCL2-driven inflammation contributes to the increased risk of breast cancer observed in women with high mammographic density." (PMID 28077158, 2017). "Population studies support the notion that increased CCL2 expression increases breast cancer risk and cancer progression." (PMID 28077158, 2017). "Together, suggest that high local or systemic IL-1β plus CXCL1 plus CCL2 plus S100A8 plus VEGF plus IL8 in breast cancer patients represents a diagnostic biomarker for the existence of IRISOE TNBC tumor, and propensity to reduced RFS, DMFS, or OS." (PMID 29262555, 2017). "Similar findings were observed with 230 samples of human breast cancer primary lesions where CCL2 expression in tumor cells and accumulating tumor associated macrophages (TAMs), increased angiogenesis, and vessel invasion of tumor cells." (PMID 28143493, 2017). "The risk of developing metastasis is significantly increased in patients with breast cancer who carry the CCL2-2518 A/G promoter polymorphism, compared to A/A homozygotes." (PMID 28077158, 2017). "Recent studies focused on breast cancer, prostate cancer, pancreatic cancer, and colorectal cancer implicated CCL2/CCR2 axis participated extensively in pathogeneses of tumorigenesis and metastasis." (PMID 26701209, 2016). "Conversely, CCL2 has been implicated in the recruitment of neutrophils into lungs of mice bearing breast cancer lung metastases, which eliminate disseminated cancer cells and diminish the formation of metastases." (PMID 25882816, 2015). "CCL2 has been implicated in promoting breast cancer metastasis as well as prostate cancer growth while TREM1 expression in hepatic satellite cells negatively correlated with disease outcome and its expression was related to aggressive tumor behavior." (PMID 26573568, 2015). "A single-cell RNA-seq analysis comparing primary and metastatic ER+ breast cancers revealed an enrichment of chemokine ligand 2-positive (CCL2+; encoded by CCL2) tumor-associated macrophages, FOXP3+ regulatory T cells, and exhausted CD8+ T cells in metastatic lesions." (PMID 41550427, 2025). "Elevated CCL2 expression in breast cancer cells is associated with early recurrence." (PMID 39749673, 2025).
breast cancer (continued). "The significant correlation between the polymorphism in the CCL2 gene and breast cancer observed in individuals with a BMI≥24 kg/m2 may result from a potential mechanism involving adipocytes within breast tissues, especially prevalent in obese populations." (PMID 39703847, 2024). "Evaluating the role of CCL2 in SMW associated with breast cancer using multiple animal models may provide further insight in developing new therapeutic strategies to treat this condition in patients with breast cancer." (PMID 38973385, 2024). "CCL2 also increased the stromal density and cancer susceptibility in a mouse breast cancer model." (PMID 38397942, 2024). "SNPs in the CCL2 gene were mainly associated with PR-positive breast cancer, whereas rs1144471 in CXCL12 was associated with ER-negative (OR=0.43, 95% CI=0.23-0.84), PR-negative (OR=0.38, 95% CI=0.19-0.74), and HER-2-positive (OR=1.27, 95% CI=1.03-1.56) breast cancer." (PMID 39703847, 2024). "Moreover, CCL2 secreted by TAMs has been linked to the induction of tamoxifen resistance in breast cancer cells through the PI3K/Akt/mammalian target of rapamycin (mTOR) pathway." (PMID 39286635, 2024). "The CCL2-2518A/G (rs1024611) polymorphism increases risk of breast cancer in the Asian population." (PMID 39703847, 2024). "However, overweight women with AA and AG+AA genotypes in CCL2 SNP rs1024611 had a higher risk of breast cancer compared to those with GG." (PMID 39703847, 2024). "CCL-2 has been associated with a poor prognosis in breast cancer and may support the formation of metastatic niches through the recruitment of monocytes." (PMID 36851213, 2023). "As shown in MR Results, CCL1 and CCL2 were risk factors for breast cancer." (PMID 38075694, 2023). "Interactions between macrophages and fibroblasts regulated by CCL2 can promote an environment that may increase breast cancer risk, leading to enhanced early tumorigenesis." (PMID 37108548, 2023). "Moreover, a strong association between high Ccl2 expression and poor survival in patients with breast cancer (triple negative) was observed when we used a larger patient dataset from KMPlotter24 (n = 126)." (PMID 37563136, 2023). "Given the convenience of diagnosis, CCL2 may be a promising clinical diagnostic marker for lung metastasis of breast cancer." (PMID 37563136, 2023). "Furthermore, IL4 signaling in macrophages regulated the transcript abundance of several other genes already causally associated with mammary cancer lung metastasis including Ccl2, Csf1, Ccr1, Hgf and Flt1." (PMID 36077870, 2022). "The pro-inflammatory factors CCL-2 and CCL-5 were reportedly associated with tumor growth, angiogenesis, and invasion of breast cancer, while CCL-2 could indirectly stimulate tumorigenic activity of normal breast cells." (PMID 35663394, 2022). "CCL2 is a diagnostic marker that can be used to predict the early recurrence of breast cancer." (PMID 36403055, 2022). "CCL2 attracts tumor-associated macrophages and is, therefore, considered as an important inductor of breast cancer progression; however, the precise mechanisms underlying its regulation by TGF-β are unknown." (PMID 34239022, 2021). "Interestingly, the level of CCL2 correlates with the presence of tumour-associated polarized M2 macrophages and poor prognosis in prostate and breast cancer." (PMID 34831015, 2021). "This study, along with the literature suggest that CCL2 could be an inflammatory driver of mammographic density and the associated breast cancer risk." (PMID 34771552, 2021). "The roles of CCL2 in breast cancer risk and fibrosis suggest that CCL2 could promote increased mammographic density." (PMID 34771552, 2021). "Moreover, NF-κB pathway activation is proved to be important for the paracrine function of tumor-derived-MSCs and cancer-associated fibroblasts in lung cancer and breast cancer in secreting CCL2, IL-6, and IL-8 in the tumor microenvironment." (PMID 33889575, 2021).
breast cancer (continued). "Notably, the serum levels of S100A14, CCL2/CXCL5 have significant diagnostic value for discerning breast cancer patients from healthy individuals." (PMID 32483412, 2020). "Previous studies have suggested that effector T cell-derived IFNγ contributes to high levels of PD-1 expression in the tumor microenvironment; CCL2 attracts monocytes, increases the number of tumor-associated macrophages and promotes angiogenesis in breast cancer." (PMID 33102239, 2020). "Analysis of 427 breast cancer specimens suggests that stromal CCL2 is associated with reduced recurrence-free survival in patients with basal-like breast cancer and may be a predictor of prognosis." (PMID 33297571, 2020). "In breast cancers, activated cancer-associated fibroblasts (CAFs) regulate the BCSCs and support stem-cell-like characteristics through factors such as monocyte chemotactic protein-1 (CCL2), IL6, IL8, and high-mobility group box 1 (HMGB1)." (PMID 32883003, 2020). "However, cessation of this CCL2/CCR2 blockade can lead to compensatory phenotype associated with increased breast cancer metastasis, for instance." (PMID 31611871, 2019). "Similarly, CCL2 expression by cancer-associated fibroblasts has been shown to support the growth of breast cancer stem cells, while CXCR4 was shown to be enriched in a subset of glioma cancer stem cells." (PMID 30873179, 2019). "Furthermore, we explored the underlying mechanisms of estrogen-triggered CCL2 regulation in ER+ breast cancer cells." (PMID 29934505, 2018). "The CCR2-64I polymorphism, which slightly impairs capacity to transduce CCL2 signals, is underrepresented in patients with breast cancer, and this might provide protection from tumour formation through reduced recruitment of tumour-promoting macrophages." (PMID 28077158, 2017). "However, further studies to dissect the contribution of macrophages to this phenotype are required to establish their role in the increased mammary cancer risk observed in Mmtv-Ccl2 transgenic mice." (PMID 28077158, 2017). "Based on these observations, we propose that CCL2-driven inflammation might play a role in increasing mammographic density and breast cancer risk." (PMID 28077158, 2017). "Furthermore, CCL2 is a key actor of metastasis since it enhances the retention of metastasis-associated macrophages in breast cancer metastasis." (PMID 28769933, 2017). "In breast cancer, CCL2 secreted from cancer-associated fibroblasts induces a CSC phenotype by activating Notch signaling, highlighting the concept that crosstalk may exist between the two axes." (PMID 28137279, 2017). "In addition, altered responsiveness to CCL2 through polymorphism in the receptor CCR2 also affects breast cancer susceptibility." (PMID 28077158, 2017). "High breast cancer CCL2 levels are associated with tumor associated macrophage (TAM) infiltration." (PMID 28143606, 2017). "Furthermore, elevated CCL2 in breast cancer patients is associated with macrophage infiltration and decreased patient survival." (PMID 25990313, 2015). "High levels of CCL2 are associated with poor prognosis in breast cancer and pancreatic cancer." (PMID 25505466, 2014). "One of those chemokines implicated in breast cancer progression is CCL2 (formerly known as MCP-1), which is a potent chemotactic factor that regulates the migration and infiltration of monocytes, memory T lymphocytes, and NK cells, signaling through CCR2 and CCR4." (PMID 25165728, 2014). "CCL2 is an important inflammatory chemokine involved in macrophage recruitment and expression of angiogenic factors that are highly expressed within breast tumors and associated with the development and progression of breast cancer." (PMID 23991131, 2013). "Together, these observations suggest that increased expression of pro-inflammatory genes such as COX2, IL-8 and CCL2 may characterize the VDRff variant in breast cancer cells as a possible clinical marker for aggressive tumors." (PMID 21283672, 2011).
breast cancer (continued). "The chemokine monocyte chemoattractant protein-1 (MCP-1)/CCL2 is a potent chemoattractant for monocytes and has been shown to play an important role in the recruitment of immunosuppressive, proangiogenic tumor-associate macrophages (TAMs) and the promotion of lung metastasis of breast cancer cells." (PMID 34698088, 2021). "Hence we speculated that PARP1 is a transcriptional regulator of CCL2 in breast cancer cells and focused on interpreting the underlying mechanisms of CCL2 regulation." (PMID 32455851, 2020). "Moreover, loss of CCL2 in early development enhances breast cancer progression." (PMID 28143493, 2017). "The disparate effects of Ccl2 versus Ccr2 disruption on the behavior of HER2/neu-driven mammary carcinomas could be due to the influence of other CCR2 ligands in CCL2-deficient mice or the effects of CCL2 on an as yet unidentified receptor in CCR2-deficient mice." (PMID 27820834, 2016). "Studies have shown that CCL2 gene expression is inhibited by 17β-estradiol, our findings may indicate that this genetic polymorphism, associated with higher levels of CCL2, is most relevant with respect to breast cancer risk against a background of low CCL2 expression." (PMID 23991131, 2013). "Taken together, AKT, p42/44MAPK and AMPK signaling are important for CCL2/HGF-mediated glycolysis in breast cancer cells." (PMID 40736024, 2025). "For instance, in breast cancer, 4T1 cells secrete GM-CSF, stimulating macrophages to produce CCL2, which recruits monocytes and promotes metastasis." (PMID 40547518, 2025). "rs2857656 (−362 G/C), rs1024611(−2518 A/G), and rs4586 (Cys35Cys) of CCL2/MCP1 are positively associated with elevated circulating levels of CCL2 and significantly associated with an increased risk of breast cancer." (PMID 41341593, 2025). "The neutralization of CCL2 with antibodies in the xenograft model of human breast cancer 4T1 cells and MDA-MB-231 cells showed a decrease in growth tumors and metastasis." (PMID 41463161, 2025). "CCL2 plays a role in tumorigenesis and metastases in several solid tumours, including breast cancer, melanoma, and prostate cancer." (PMID 40385641, 2025). "CCL2 was shown to promote breast cancer brain metastasis and the invasion and adhesion of SK-OV-3 cells." (PMID 41279931, 2025). "Cancer-associated fibroblasts (CAFs) have been shown to enhance the stem-like properties of breast cancer cells via the CCL2/NOTCH1 signaling pathway." (PMID 40485724, 2025). "In fact, the secretion of CCL2 by tumor cells has been observed in a variety of cancer types, such as esophageal carcinoma, bladder cancer, breast cancer, melanoma, and colorectal cancer (CRC), leading to enhanced TAM infiltration in TME." (PMID 40380196, 2025). "CCL2 and HGF co-treatment enhanced breast cancer cell growth, survival, and invasiveness over individual CCL2 or HGF treatment." (PMID 40736024, 2025). "CCL2 has been identified as a critical factor on the surface of EVs derived from metastatic breast cancer cells." (PMID 40343498, 2025). "Recent research has provided evidence that β‐catenin signaling can regulate CCL2 expression in breast cancer cells and in the human chondrocyte cell line." (PMID 40012719, 2025). "In young mice bearing 4T1 mammary tumors, calcitriol elevated levels of the chemokine CCL2 in both plasma and tumor tissues." (PMID 41374952, 2025). "In mammary tumors, Ccl2, Ccl3 and Ccl5 were shown to modulate the infiltration of monocytes, resulting in the accumulation and activation of tumor-associated macrophages, TAMs." (PMID 39566333, 2025). "A correlation between CCL2 expression and lung metastasis has also been shown in breast cancer patients." (PMID 40343498, 2025). "In a breast cancer model, tumor and stromal-derived CCL2 induces the recruitment of inflammatory monocytes, while the inhibition of CCL2 signaling blocks this recruitment resulting in attenuation of metastasis." (PMID 39566333, 2025).
breast cancer (continued). "ELISA results indicate genotype-dependent differences in CCL2 expression across breast cancer cell suspensions, with an inverse correlation to ER and PR status." (PMID 40909271, 2025). "Overexpression of CCL2 enhances stemness and macrophage polarization in breast cancer via STAT3 and Notch-1 signaling cascade, whereas silencing it increases tumor necrosis and autophagy, resulting in reduced CSC population and macrophage recruitment." (PMID 39858015, 2025). "Recent clinical data suggest that there is a strong relationship between CCL2 expression and poor prognosis in various types of cancer, including breast cancer." (PMID 40343498, 2025). "While alterations in glutamine/glutamate have been reported in breast cancers, this pathway was of lower impact than glucose metabolism in CCL2/HGF co-treated cells." (PMID 40736024, 2025). "Particularly, TAM-produced CCL2 in the context of breast cancer microenvironment activates AKT/beta-catenin signaling resulting in EMT and CSC properties in TNBC." (PMID 39981232, 2025). "CCL2-secreting breast cancer cells have been shown to interact with CCR2+ macrophages to facilitate their metastasis to lung and bone." (PMID 39996058, 2025). "The median plasma CCL2 level was 19.99 pg/mL (range: 1.95–64.87 pg/mL) in healthy controls and 28.15 pg/mL (range: 9.01–49.15 pg/mL) in the breast cancer testing group." (PMID 39749673, 2025). "In murine breast cancer models, 7-isopentenyloxycoumarin has been found to exhibit potent antiangiogenic activity by modulating CCL2 chemokine signaling, leading to decreased tumor vascularization and growth." (PMID 40430886, 2025). "CCL2 + EVs derived from metastatic breast cancer cells are more likely to be taken up by CCR2 + macrophages in lung tissues, which is consistent with our findings." (PMID 40343498, 2025). "Elevated plasma chemokine (C–C motif) ligand 2 (CCL2) levels distinguished patients with breast cancer from healthy controls." (PMID 39749673, 2025). "Our study confirms elevated CCL2 levels exist in patients with breast cancer relative to healthy controls with large overlapping CCL2." (PMID 39749673, 2025). "Recent reports have shown that metastatic breast cancer cells secrete CCL2 protein encapsulated in EVs." (PMID 40343498, 2025). "In summary, circulating CD3+CD8+ CTL and plasma CCL2 levels emerged as promising dual‐purpose biomarkers and therapeutic targets in breast cancer management." (PMID 39749673, 2025). "Consistent with our results, recent accumulating evidence has suggested that CCL2 plays a crucial role in the lung metastasis of breast cancer." (PMID 40343498, 2025). "The chemokine CCL2/MCP-1, has been shown to promote breast cancer progression and metastasis to lungs and bone in mouse models of breast cancer." (PMID 41279138, 2025). "Among analyzed cytokines, CCL2 fold change was the one that increased the most remarkably (12.7 times vs. control) in the melanoma model in comparison to the breast carcinoma model (3.7 times vs. control)." (PMID 39857957, 2025). "First, CCR2-KO or Merestinib treatment alone reduced the growth and survival of mammary carcinomas and inhibited M2 macrophage recruitment, indicating disruptions to CCL2 and HGF signaling with inhibition of CCR2 or MET." (PMID 40736024, 2025). "Namely, mice with melanoma tumors demonstrated higher levels of CXCL10, IL-6, and CCL2 in the serum compared to mice with control breast carcinoma tumors." (PMID 39857957, 2025). "Association of CCL2 and CXCL12 gene SNPs with lymph node metastasis and histological grade of breast cancer." (PMID 39703847, 2024). "BALB/c mice models implanted with 4 T1 mammary tumor cells were treated with 6‐shogaol (30 mg/kg of body weight) for 14–21 days, decreasing CCL2 in TADCs and reducing metastasis." (PMID 39055196, 2024). "CCL2 (CC chemokine ligand 2) has been shown to play a key role in the growth, invasion, and metastasis of breast cancer cells." (PMID 39703847, 2024).